MMP1 (matrix metallopeptidase 1)
Diseases named in the same sentence as MMP1 in open-access papers (continued):
Sharing a sentence is not in itself a finding about the gene and the disease.
aging (12 papers, 2016 to 2025). A developmental process that is a deterioration and loss of function over time. "In particular, skin photo-aging is associated with the acceleration of collagen degradation by the intracellular activity of MMP1 26-28." (PMID 39494335, 2024). "As MMPs are known to cause skin aging through the degradation of collagen, we also examined the activity of MMP-1 and the expression levels of MMP-1, MMP-2, and MMP-9." (PMID 30669248, 2019). "Previous studies showed that UVB-induced ROS cause skin aging by activating MMP-1." (PMID 30934595, 2019). "Increased MMP-1 activity during skin aging results in a reduction in fibrillin-rich microfibrils, which play a crucial role in maintaining skin elasticity and integrity." (PMID 37958946, 2023). "A prior study showed that BDB, as a preventative measure against skin photo-aging, reduced MMP-1 expression and inhibited MAPK pathway activation in UVB-induced HaCaT keratinocytes." (PMID 36135752, 2022). "Skin aging is caused by collagen degradation via MMP-1 activation, and our results show significant variations in soluble collagen content and MMP-1 expression in the skin tissues after UV stimulation." (PMID 34122721, 2021). "Skin aging induced by ultraviolet (UV) irradiation increases expression of matrix metalloproteinase-1 (MMP-1) and destroys collagen fibers, as a result accelerating wrinkle formation." (PMID 34451713, 2021). "Studies conducted by our team and others over the past several years have shown that MMP-1 (collagenase) is significantly elevated in both naturally-aged skin and in sun-induced premature skin aging (photoaging)." (PMID 27104752, 2016). "Since circadian clock component PER can regulate MMP-1 expression, it might be a new molecular mechanism to develop therapeutics to alleviate skin aging and skin cancer." (PMID 29570674, 2018). "The increase of MMP-1 and MMP-3 leads to excessive degradation of collagen, which is an essential factor leading to skin aging." (PMID 36364921, 2022). "MMP-1 and MMP-9 are known to play a critical role in skin aging via collagen degradation." (PMID 32414118, 2020).
non-small cell lung carcinoma (12 papers, 2013 to 2025). A group of at least three distinct histological types of lung cancer, including non-small cell squamous cell carcinoma, adenocarcinoma, and large cell carcinoma. "MMP1 is also linked to resistance in erlotinib-treated non-small cell lung cancer (NSCLC), where its high expression correlates with poor survival outcomes, suggesting it as a marker of erlotinib resistance." (PMID 40287412, 2025). "In addition, increased MMP1 expression was related to IPF associated with non-small cell lung cancer in a recent work." (PMID 35203313, 2022). "In non-small cell lung cancer H460 and A549 cells, LicA could suppress migration and invasion through a reduction in MMP-1 and MMP-3 expression." (PMID 36840005, 2023). "Indeed, KDELR2 overexpression promotes the metastatic phenotype in non-small cell lung cancer (NSCLC) by increasing MMP1, MMP2 and MMP9 secretion and thus cell invasive ability." (PMID 35399533, 2022).
endometriosis (11 papers, 2006 to 2025). The growth of functional endometrial tissue in anatomic sites outside the uterine body. "The association of MMP-1 and MMP-3 with the SASP and endometriosis pathophysiology prompted us to investigate the levels of these ECM components in our samples using the Luminex xMAP technology." (PMID 40834152, 2025). "MMP1 is overexpressed in endometriotic tissues, suggesting its involvement in the pathogenesis of endometriosis." (PMID 32299427, 2020). "Remarkably, several MMP genes (MMP1,2,3,10,11,14) were found overexpressed and specific for endometriosis, possibly providing a biological explanation for the propensity of these cells to invade the surrounding tissues." (PMID 19055724, 2008). "Increased levels of MMP-1, MMP-2, and MMP-3 in endometriotic lesions indicate that endometriosis may have a unique metabolomic signature linked to cell cycle arrest and inflammation." (PMID 40834152, 2025). "The increased levels of MMP-1, MMP-2, and MMP-3 in endometriotic lesions observed in this study indicate that endometriosis may have a distinct metabolomic signature linked to cell cycle arrest and inflammation." (PMID 40834152, 2025). "It has been reported that ERβ plays an important role in EMS pathogenesis by modulating its target genes, including NRF1, SOD2, COX2, and MMP1, and specific ERβ suppression, such as ERβ antagonist, has been used for treatment of endometriosis, but with many of limitations and side effects." (PMID 33362719, 2020). "Interestingly, MMPs are prominently represented, with 6 family members (MMP1, 2, 3, 10, 11, 14) present among the top 20 endometriosis-specific genes." (PMID 19055724, 2008). "Additionally, IL-1β is recognized for its role in amplifying the inflammatory response by upregulating MMP12, MMP1, PAI2, and other cytokines and growth factors, thereby fostering neovascularization as well as matrix remodeling, which are implicated in the development of endometriosis." (PMID 40303639, 2025). "MMP1 was expressed in most of the present endometriotic samples, in agreement with previous reports of MMP overexpression in women with endometriosis and more severe stages of this disease." (PMID 38069001, 2023). "Several MMPs such as MMP1, MMP2, MMP 3, MMP10, MMP 11, and MMP 14 are identified as endometriosis-specific genes." (PMID 19055724, 2008). "Whereas, overexpression of MMP1 is reported in endometriotic tissues, however, the roles of MMP1 regarding the pathogenesis of endometriosis has not been elucidated yet." (PMID 32299427, 2020). "Comparison of the endometriosis gene expression profiles with the gene expression patterns observed in normal human tissues allowed the identification of endometriosis-specific genes, which included several members of the MMP family (MMP1,2,3,10,11,14)." (PMID 19055724, 2008).
preeclampsia (11 papers, 2013 to 2024). Preeclampsia is a hypertensive disorder of pregnancy that is characterized by new-onset hypertension with proteinuria presenting after 20 weeks of gestation, and depending on mild or severe forms may initially present with severe headache, visual disturbances, and hyperreflexia. "We also observed that the fetal genotype elevates the maternal risk of preeclampsia development (OR = 6.54, 95% CI 2.13–20.01; p < 0.01) for simultaneous carriers of 1G/1G MMP1 and 5A/6A MMP3 polymorphisms." (PMID 29670668, 2018). "The occurrence of 1G/1G MMP1 or 5A/5A MMP3 genotype in the mother or 1G/1G MMP1 or 5A/6A MMP3 genotype in the child is associated with preeclampsia development." (PMID 29670668, 2018). "This study explored whether reduced MMP-1 expression is associated with shallow trophoblast invasion and the pathogenesis of preeclampsia." (PMID 25667666, 2015). "However, this study was the first step in exploring the association between MMP-1 and preeclampsia." (PMID 25667666, 2015). "MMP-1 is significantly elevated 10 weeks before clinical symptoms of preeclampsia appear, a time when the women are thought to have a normal pregnancy." (PMID 35563315, 2022). "This study aimed to assess the potential role of MMP1, MMP9, TIMP1 and TIMP2 gene polymorphisms in the pathogenesis of preeclampsia." (PMID 35885543, 2022). "The simultaneous carriage of 1G/1G MMP1 and 5A/5A MMP3 polymorphisms by mother increases over 10-fold her risk to preeclampsia development." (PMID 29670668, 2018). "To summarize, our findings suggest that maternal SNPs −1607 1G/1G MMP1 and −1171 5A/5A MMP3 are independency important genetic factors associated with the occurrence of preeclampsia in Polish population." (PMID 29670668, 2018). "These analyses revealed that simultaneously maternal homozygosity in 1G/1G MMP1 and 5A/5A MMP3 increases the risk of preeclampsia development over 10-fold (OR = 10.22, 95% CI 2.28–45.8; p < 0.01)." (PMID 29670668, 2018). "The fetal set of 1G/1G MMP1- and 5A/6A MMP3-studied polymorphisms also contributes to maternal predisposition of occurrence of preeclampsia OR = 6.54 (95% CI 2.13–20.01, p < 0.01)." (PMID 29670668, 2018). "Some studies note that the reduction of MMP1 levels in the umbilical cord blood, placenta, and decidua is characteristic for patients whose gestation is accompanied by preeclampsia." (PMID 29670668, 2018). "We found that many genes from the MMP family have different methylation patterns among the study groups; MMP-1, -8, -12, -13, -21 and -26 were hypomethylated in the promoter region in the samples from women with preeclampsia." (PMID 28726716, 2017). "We further evaluated the effect of hypomethylation of MMP-1 in cultured vascular smooth muscle cells stimulated with neutrophils as an in vitro model of preeclampsia showing a strong correlation with the increase of MMP-1 gene expression." (PMID 28726716, 2017). "We evaluated the role of MMP-1 in preeclampsia, showing a high level of this MMP in the vasculature of women with this pathology, suggesting a role in the vascular collagen breakdown that possibly favors the edema and proteinuria observed in these patients." (PMID 28726716, 2017). "In this study, investigation of protein expression at the maternal-fetal interface revealed that MMP-1 was decreased in the umbilical serum, placenta and decidua of the patients with preeclampsia compared with the controls." (PMID 25667666, 2015). "Reduced MMP-1 levels in the umbilical serum, placenta and decidua were observed in women who developed preeclampsia." (PMID 25667666, 2015). "The positive rates of expression of MMP-1 in the placenta of the normal, gestational hypertension, mild preeclampsia and severe preeclampsia groups were 96.7, 77.8, 66.7 and 23.1%, respectively." (PMID 25667666, 2015).
preeclampsia (continued). "Their importance in proper invasion of trophoblast cells is highlighted by the observation that MMP1, 3 and 7 are downregulated in EVTs of patients with preeclampsia and intrauterine growth restriction." (PMID 24923321, 2014). "The protein expression of MMP-1 in extravillous trophoblast is decreased in preeclampsia." (PMID 37017519, 2023). "Circulating neutrophil elastase, MMP-1 and thrombin are all elevated in preeclampsia." (PMID 35563315, 2022). "The present study examines whether the occurrence of single-nucleotide polymorphisms (SNP) in the MMP1, MMP2, MMP3, and MMP9 genes is related to the outcome of preeclampsia." (PMID 29670668, 2018). "The maternal 1G/1G MMP1 and 5A/5A MMP3 and fetal 1G/1G MMP1 and 5A/6A MMP3 gene polymorphisms may be strong genetic markers of preeclampsia, occurring either individually or together." (PMID 29670668, 2018). "The aim of the present study was to determine whether the most common MMP1, MMP2, MMP3, and MMP9 gene polymorphisms in maternal and fetal genes are associated with preeclampsia." (PMID 29670668, 2018). "In this work we also demonstrated that MMP-1 secreted by vascular smooth muscle cells induces the release of interleukin-8, which favors the recruitment of activated neutrophils in women with preeclampsia, and the consequent generation of reactive oxygen species." (PMID 28726716, 2017). "The levels of MMP-1 in the umbilical serum of the normal, gestational hypertension, mild preeclampsia and severe preeclampsia groups were 294.33±11.53, 247.78±20.32, 177.67±12.63 and 124.68±15.41 pg/ml, respectively, and there were significant differences between each two groups (P<0.05)." (PMID 25667666, 2015). "There are at least three proteases elevated in preeclampsia that activate PAR-1, neutrophil elastase, matrix metalloproteinase 1 (MMP-1) and thrombin." (PMID 35563315, 2022). "TNF-alpha induces collagen I deposition in the maternal vasculature, and MMP1 and -7 activity induce extracellular matrix degradation, while CYP2J2, elevated in preeclampsia, may also be involved in uteroplacental and vascular remodeling." (PMID 31252672, 2019). "The aim of the present study was to explore the levels of matrix metalloproteinase-1 (MMP-1) and tissue inhibitor of metalloproteinase-1 (TIMP-1) in the maternal umbilical serum, placenta and decidua of patients with preeclampsia compared with those in normotensive pregnant females." (PMID 25667666, 2015).
pterygium (11 papers, 2011 to 2025). A wedge-shaped fibrovascular lesion arising from the bulbar conjunctiva and extending to the cornea. "Subconjunctival, head, and body fibroblasts from pterygium display high expression of two distinctive forms, MMP-1 and MMP-3." (PMID 40565017, 2025). "In advanced pterygium, MMP-1 expressed by fibroblasts is localized at the borders of the Bowman’s layer and corneal epithelium." (PMID 40565017, 2025). "MMP-1 was found to be expressed by pterygium-diseased cells dissolving Bowman’s layer and thereby playing a key role in the formation and migration of pterygium." (PMID 38006824, 2023). "The expression of MMP1, an important factor in corneal collagen degradation, in pterygium head fibroblasts is higher than that in the body and conjunctiva, which creates conditions for degradation of the exposed elastic layer by MMP2." (PMID 33790949, 2021). "Previous studies have confirmed that PFD decreases autocrine expression of TGF-β and MMP-1 in human pterygium fibroblasts and inhibits the production of collagen I in human intestinal fibroblasts." (PMID 33874948, 2021). "MMP-1 is one of six MMPs found in the limbal basal cells affected by pterygium, which are also present in invasive tumors." (PMID 34206333, 2021). "It is possible that matrix-bound MMP-1 forms a reservoir of latent enzyme in pterygium epithelial cells." (PMID 32218695, 2020). "Expression of MMP-1 has been detected in pterygium fibroblasts found between the corneal epithelium and BL at the edge of the advancing pterygium." (PMID 28068383, 2017). "It has been reported that the expression of several types of MMPs (MMP-1, 2, 3, 7, and 9) increases in pterygium and related cell types (fibroblasts and epithelial cells)." (PMID 21224999, 2011). "Additionally, pterygium cells stimulate local fibroblasts and facilitate the cleavage of fibrillar collagen through the activities of MMP-1 and -3." (PMID 40565017, 2025). "In some reports of pterygium, when determining MMP-1 and its inhibitor TIMP-1, the latter was observed at levels similar to those of MMP-1, which could explain the progressive-invasive growth of the pterygium." (PMID 34361655, 2021). "As MMP-1 is localized in pterygium-diseased cells that invade the cornea, it is hypothesized that MMP-1 is involved in the pathogenesis by facilitating Bowman’s membrane dissolvement, thereby enabling the migration and local infiltration of pterygial cells." (PMID 34206333, 2021). "In pterygium, the overexpression of MMP-1 breaks the balance between MMP-1 and TIMP-1, and the imbalance may cause pterygium to infiltrate through the normal cornea 44,45." (PMID 32218695, 2020). "Interestingly, bevacizumab significantly reduced the expression of MMP-1 in cultured Tenon’s fibroblasts from primary and recurrent pterygium." (PMID 28068383, 2017). "Bevacizumab also suppresses MMP-1 expression in Tenon’s fibroblasts derived from recurrent pterygium and inhibits MMP-3 and -13 in in vivo pterygium tissue." (PMID 40565017, 2025). "Among the less abundant MMP types, MMP-1, -7, and -3 are found in human pterygium fibroblasts in vitro; however, MMP-1, -2, and -9 are specifically expressed in pterygium tissue." (PMID 40565017, 2025). "Disruption in the equilibrium between MMP-1 and TIMP-1 contributes to pterygium invasion into corneal cells and tissue." (PMID 40565017, 2025). "Other authors also detected increased levels of MMP-1 and MMP-3 in pterygium head fibroblasts, initiating corneal invasion." (PMID 38006824, 2023). "By activating this pathway, different growth factors, such as matrix metalloproteinase-1 (MMP-1), interleukins and VEGF, which play a crucial role in the pathogenesis of pterygium, are also activated." (PMID 38006824, 2023).
renal fibrosis (11 papers, 2014 to 2024). A final common manifestation of a wide variety of chronic kidney diseases characterized by glomerulosclerosis and tubulointerstitial fibrosis. "In particular, in PNx mice that received EVs pre-treated with the MMP1-blocking antibody, a decreased capacity of EVs to reduce renal fibrosis was observed at the histological level." (PMID 39062090, 2024). "Moreover, the inhibition of matrix metalloproteinase (MMP)-9 and decreased expression of MMP-1 resulted in decreased histological evidence of renal fibrosis." (PMID 36176443, 2022). "MMP-1 inhibits renal fibrosis by regulating the degradation of extracellular matrices." (PMID 35646873, 2022). "Early changes (increases) in MMP-1 concentrations post-CXCL12 injection may play a role in the attenuation of renal fibrosis with CXCL12 treatment, but our small sample size (n = 1) precludes us from making this conclusion." (PMID 33748219, 2021). "There is only a little data concerning the role of MMP-1 in renal fibrosis." (PMID 32670438, 2020). "Thus, we speculated that MMP2 and MMP9 play a role in the formation of polycystic kidney lesions and renal fibrosis in a different way from MMP1." (PMID 24595031, 2014).
adenoma (10 papers, 2006 to 2025). A neoplasm arising from the epithelium. "The experimental results confirmed a close and strong correlation between MMP-3, MMP-1 polymorphisms, and adenomas." (PMID 38203373, 2023). "Lièvre examined gene promoter polymorphism mainly in MMP-3, but also in MMP-7 and MMP-1 in patients with adenomas." (PMID 38203373, 2023). "The authors suggested that only the study MMP-3 and MMP-1 gene promoter polymorphisms had potential roles in the development of adenomas from normal colon epithelial cells or in the earliest steps of CRC." (PMID 34944846, 2021). "The analysis revealed a significant association between MMP-3-1612 ins/del A, MMP-1-1607 ins/del G polymorphism, and small adenomas; also, adenomas were associated with the combined genotype 2G/2G-6A/6A." (PMID 34944846, 2021). "MMP1 expression was significantly higher in adenomas (mean 1.93) compared to adenocarcinomas (mean: 1.69, p = 0.017)." (PMID 40699620, 2025). "This difference was further supported by paired analysis, where 64% of patients exhibited higher MMP1 expression in adenomas relative to their matched malignant samples." (PMID 40699620, 2025). "A previous study tried to determine the usefulness of MMP1 for differential diagnosis of follicular thyroid lesions, particularly between minimally invasive carcinoma and adenoma." (PMID 36479070, 2022). "Furthermore, senescence-associated ECM remodeling genes (MMP1, 9, and 10 and TIMP1 and 2) exhibited increased levels in adenomas in relation to their matched malignant tissues where MMP10 was high in most of the samples." (PMID 40699620, 2025). "Although we could identify areas of intense over-expression of both M3R and MMP1 in adenoma and adenocarcinoma tissue, we were unable to quantify the relationship between such changes consistently." (PMID 28416748, 2017). "Applying immunofluorescence to determine the relationship between M3R and MMP1 expression in normal colon, adenoma, and adenocarcinoma from the same individual appeared to show the redistribution of MMP1 staining from glandular lumens in normal colon to cell surfaces in cancer." (PMID 28416748, 2017). "Furthermore, MMP1, which is also a WNT/Beta-catenin target, was upregulated in our adenoma-normal and cancer-normal comparisons." (PMID 31211760, 2019).